CDK4 (cyclin dependent kinase 4)
Diseases named in the same sentence as CDK4 in open-access papers (continued):
Sharing a sentence is not in itself a finding about the gene and the disease.
tumor (continued). "Importantly, we provide evidence that cyclin D-overexpressing cells do not show enhanced sensitivity to CDK4/6 inhibition and thus question their therapeutic potential in targeting cyclin D-overexpressing tumours." (PMID 28177473, 2017). "Substantial reduction of tumour growth was observed in p16/p21-DKO mice but not in mice lacking either p16Ink4a or p21Cip1/Waf1 (single KO mice), suggesting that both CDK2 and CDK4 associate with this transcription factor in a complementary fashion." (PMID 29234059, 2017). "The interaction of STK11 with CDK4 leads to the hypothesis that the tumour suppressor function of STK11 may be in part mediated by engaging the cell cycle regulatory machinery through its direct interaction with and inhibition of CDK4 activity." (PMID 28205554, 2017). "Tetraploid cells do not exhibit increased sensitivity to abemaciclib, suggesting that cyclin D-overexpressing tumours might not be specifically amenable to treatment with CDK4/6 inhibitors." (PMID 28177473, 2017). "Having shown that CDK4 regulates BCSCs expansion and promotes BCSC self-renewal capacity, we next investigated the potential role of CDK4 in BCSC chemotherapy resistance, with a long term goal of identifying potential new clinical therapeutic approaches for tumor relapse in TNBC patients." (PMID 27759034, 2016). "Therefore, CDK4/6- and IGF-1R-inhibitors were tested on this patient's tumor in the PDOX model." (PMID 27286459, 2016). "Similarly, this has been seen in the case of CDK4 where it is not amplified in the well-differentiated component of a tumor and amplified in the dedifferentiated component." (PMID 25822339, 2015). "Given that CDK4/6 inhibitors have been most effective in the context of functional RB1 and low expression or deletion of p16 in other tumor types, these data suggest such agents may merit evaluation in HPV-negative SCCHN, specifically in cases associated with high pT356RB1." (PMID 26265441, 2015). "The observed anti-tumor activities of celastrol and its derivatives both in vitro and in vivo promoted degradation and decreased phosphorylation of protein kinases that are known to be highly activated in HCC cells, such as Raf family proteins, AKT, MEK1/2, CDK4, and EGFR." (PMID 25051375, 2014). "However, positive CDK4 IHC immunoreactivity was not different according to tumor recurrence in all cases (p = 0.363), and in each histological subtypes (p = 0.128 in WD, p = 0.576 in DD)." (PMID 25121597, 2014). "Combination studies illustrated that CDK4/6 inhibition is cooperative with multiple Her2-targeted agents and provides a complementary mechanism of action to T-DM1 to efficiently suppresses the proliferation of residual Her2-positive tumor cell populations that survive T-DM1." (PMID 25221644, 2014). "However, it is also clear that there are features of tumor behavior that we do not fully understand, as specific diseases which frequently lose p16ink4a had minimal response to CDK4/6 inhibitors in the clinic." (PMID 25156567, 2014). "By using 2D-gel electrophoresis to separate the phosphorylated forms of CDK4 and CDK6 bound to their regulatory partners, we have identified the activating T172 phosphorylation as the last, separately regulated, critical step of CDK4 activation in such tumor cells and in various normal cells." (PMID 23737759, 2013). "Furthermore, our results demonstrate that miR-34a can also regulate tumor angiogenesis by directly inhibiting angiogenic functions of endothelial cells by downregulating a number of key proteins including E2F3, SIRT1, survivin and CDK4." (PMID 22629428, 2012). "Even though resistant tumor cells can escape immune recognition from γδ T cells by down regulating surface expression of MICA, γδ T cells can still be able to slow down the progression of the tumor cell proliferation by inhibiting cell cycle related molecules CDK2, CDK4 and Cyclin D1." (PMID 21935360, 2011).
tumor (continued). "As we excluded any association of the CDK4 IVS4-nt40 AA genotype with the subset of non-obese cancer and tumor/cancer cases, we were able to further confirm the validity of the identified association with the obese-associated cancer and tumor/cancer cases." (PMID 19327170, 2009). "The expressions of cyclin D1, cyclin E, cyclin-dependent kinase 4 (CDK4), and CDK2 were immunohistochemically examined in 90 patients with human oesophageal squamous cell carcinoma (SCC) to determine their relationship to the tumour behaviour and patient prognosis." (PMID 10390005, 1999). "The evidence presented in this case report strengthens the argument that CDK4/6 may play an important role in the pathogenesis of CDK4-amplified ARMS and that abemaciclib in combination with temozolomide and irinotecan may abrogate tumor growth and improve outcomes." (PMID 40936693, 2025). "Notably, among the top-ranked CTD-suppressed genes, we found that five genes, including TOP2A, ACSL4, SQLE, CDK4, and SLC6A14 were significantly elevated in HCC clinical specimens, suggesting that NCTD targets to inhibit the expression of these genes to exert anti-tumor effects in HCC." (PMID 40271060, 2025). "Consequently, maintaining CDK4/6i appears to slow tumor growth rather than completely arrest it." (PMID 39605351, 2025). "However, no strong predictors exist for tumor response to CDK4/6i." (PMID 40731908, 2025). "Likewise, YAP/TAZ is known to drive tumor proliferation and resistance in response to a variety of targeted therapies, including EGFR, Anaplastic Lymphoma Kinase (ALK), Mitogen-activated protein kinase (MEK), and Cyclin-dependent kinase 4/6 (CDK4/6) inhibitors." (PMID 38607003, 2024). "In addition, senescent cancer cells by other types of DNA damaging agents (Etoposide and Carboplatin) and CDK4/6i (Abemaciclib) also showed similar trends of mRNA expression pattern in pro‐inflammatory SASP, pro‐angiogenic factors, and anti‐tumor immune‐related genes." (PMID 37854019, 2024). "This may serve as a cautionary note for the identification of ALM patients who may benefit from CDK4i/6i based solely on tumor sequencing, which may prevent patients with elevated CDK4/CDK6 protein expression but no clear evidence of copy number variation in CDK4/6 pathway genes from treatment." (PMID 38066089, 2024). "Moreover, as the dysfunction of cyclin D1 E3 ligases is involved in desensitizing of cancer cells towards CDK4/6is in clinical practice, we utilized MG53 in combination with palbociclib and successfully enhanced the sensitivity of cancer cells to palbociclib and further repressed tumor growth." (PMID 37414783, 2023). "Our analysis suggests that expression/activation of CDK4/6 substrates in tumor cells and genomic-independent activation of the AKT/mTOR pro-survival signaling pathway in tumor and surrounding stroma/immune cells may predict response to CDK4/6 inhibition in combination with ET in MBC." (PMID 36797347, 2023). "Indeed, in the MonarchE trial, patients with ≥4 positive nodes or 1 to 3 positive nodes and either tumour size ≥5 cm, histologic grade 3, or central Ki-67 ≥20% were randomised to receive adjuvant endocrine therapy (ET) with or without a CDK4/6 inhibitor (abemaciclib)." (PMID 37623023, 2023). "Therefore, replication stress may be ongoing in patients during the periods of CDK4/6 inhibitor treatment, assuming that not all tumour cells will be held fully in G1 throughout this treatment period." (PMID 35037284, 2022).
tumor (continued). "Therefore, dual targeting of CDK4/6 and IGF1R could play an effective role in providing a candidate synergistic combination for clinical application in this disease and promoting inhibition of the cell cycle as well as PI3K/mTOR axis in tumor cells." (PMID 36266723, 2022). "Thus, although contamination by nontumor tissue may have led us to overlook some additional potential biomarkers, it does not affect our conclusions about the involvement of CDK4 and filamin A in sensitizing tumour cells to paclitaxel." (PMID 36477027, 2022). "The expanding clinical application of CDK4- and CDK6-inhibiting drugs in the management of hormone-sensitive breast cancer has raised a great interest in also testing these G1/S cell-cycle blocking agents in other neoplasms, for which the potential clinical benefit is still largely unknown." (PMID 34445095, 2021). "In general, high expression of CDK4/6 might have a negative impact on the immune microenvironment, which inhibits the infiltration and activation of immune cells and reduces the antigen presentation ability of tumor cells." (PMID 35095879, 2021). "Additional combination treatment approaches, including radiation therapy, chemotherapeutic agents, the CDK4 inhibitors palbociclib, the PARP inhibitors rucaparib and the MEK inhibitor trametinib, may be needed to maximize the eradication of tumor cells and mitigate the tumor recurrence." (PMID 34732238, 2021). "Moreover, there is increasing evidence showing the immunomodulatory effects of CDK4/6is in vivo, including enhanced antigen presentation, increased infiltration of CD8+ T cells and reduced regulatory T cell (Treg) proliferation, which are beyond tumor cell cycle control 11-13." (PMID 32929370, 2020). "Interestingly, CDK4 gene expression was higher in luminal B and basal-like CCND1-amplified tumours only (“CDK4” P = 0.004 and P = 0.029 respectively) whilst CDK6 expression was lower in luminal A, luminal B and HER2-enriched CCND1-amplified tumours (“CDK6” P < 0.001 for all comparisons)." (PMID 30819233, 2019). "MDM2 and CDK4 immunostaining are not specific for diagnosis but could be expressed by tumor cells." (PMID 31299983, 2019). "Having found that CDK4 but not CDK6 could regulate MET and the phenotype of the cells, we next investigated the potential role of CDK6 in regulating cancer stemness in TNBC and its potential association with tumor progression and outcomes." (PMID 27759034, 2016). "In contrast, mutations and CN alterations affecting cell cycle regulators, such as MYCN, CDK4 and CDKN2A/B, except for MDM2, were particularly enriched in the A1/A2 clusters compared with the E1/E2 clusters (P=0.016), suggesting that these genes may have driver roles in A1/A2 tumours." (PMID 26138366, 2015). "Moreover, overexpression of cyclin D1 alone may also contribute to tumour progression independent of CDK4 overexpression." (PMID 10390005, 1999). "In this case, spindle and stellate tumor cells were strongly positive for vimentin and CD34, and negative for CK, desmin, SMA, HMB-45, MDM2, CDK4, p16, β-catenin, and STAT6." (PMID 41458523, 2025). "On IHC, atypical spindle cell/ pleomorphic lipomatous tumor shows variable positivity for CD34, S100 protein, and desmin, while MDM2 and CDK4 are often negative." (PMID 38916002, 2024). "Immunohistochemical staining indicated that the tumor cells were positive for murine double minute 2 (MDM2) and cyclin-dependent kinase 4 (CDK4), and negative for pleomorphic adenoma gene 1 (PLAG1)." (PMID 39109289, 2024). "Immunobiologically, the nuclei of the tumor cells were positive for murine double minute (MDM), weakly positive for cyclin-dependent kinase 4 (CDK4) and smooth muscle actin (SMA), and negative for KIT, CD34, S100, and Desmin." (PMID 39297994, 2024).
tumor (continued). "Immunohistochemical analysis demonstrated the positive expression of S100A4, CDK4, MDM2, CD34, and Vimentin, along with the negative expression of Leptin, confirming the tumor’s high aggressiveness and malignancy." (PMID 39591300, 2024). "No immunoreactivity for CK, S100, CD31, ERG, MDM2, CDK4, Melan A, or HMB45 was detected in the tumor cells." (PMID 38388450, 2024). "Since most MPM tumours lacking phospho‐CDK4 had high p16 expression, appropriately scored p16 immunohistochemistry (especially regarding intensity and homogeneity of expression), possibly in combination with proliferation markers, could also be used to exclude those intrinsically resistant tumours." (PMID 36453028, 2024). "In particular, if a tumor is located in the deep tissue or imaging findings are not typical, the possibility of ALT should be considered and immunohistochemistry for MDM2 and CDK4 are mandatory." (PMID 39109289, 2024). "Since the tumor was hormone receptor positive and HER‐2 negative, she was offered, as adjuvant‐like treatment, a combination of CDK4/6 inhibitor with endocrine therapy, tolerating the treatment well and being disease‐free in her last follow‐up." (PMID 39021492, 2024). "Unlike the already-marketed CDK4/6 anti-tumor inhibitors, BEBT-209 improves the selectivity of CDK4 over CDK6, which is expected to reduce the hematological and immunosuppressive toxicity caused by CDK6 activity inhibition." (PMID 38138549, 2023). "A more recently published study, using a different method, showed a correlation of tumor fraction in cfDNA with PFS but not OS, in case evaluated before CDK4/6i initiation." (PMID 38001722, 2023). "Patient selection by high mRNA expression of CDK4, while CDKN2A was not overexpressed at baseline tumor followed an extensive investigation." (PMID 37875500, 2023). "WNT4 had decreased expression (logFC = −1.6), and the expression of seven mRNAs (CDK4, MAPK1, TGFB, ZEB2, AURKA, SOX4, and ADAM9) in tumor samples was not notably different from that in the group of normal tissues." (PMID 35453574, 2022). "The tumor is typically negative for MDM2 and CDK4 or show only focal weak staining, with consistent absence of MDM2 and CDK4 amplification." (PMID 34089125, 2022). "In addition, recent evidence demonstrates that treatment of tumors with CDK4/CDK6 inhibitors could restore regulatory mechanisms, including regulation of IFNγ signaling, antigen presentation machinery and cell release of immunomodulating factors, leading to improve the immune anti-tumor activity." (PMID 34299136, 2021). "Teo’s study showed that CDK4/6 inhibitors combined with PI3K inhibitors increased the apoptosis of triple-negative breast cancer cell lines and induced persistent tumor regression in vivo." (PMID 32357912, 2020). "Although we discovered that CUEDC1 inhibited Bcl-2, C-myc, CyclinD1 and CDK4 expression and facilitated Bax expression, we did not fully elucidate the detailed mechanism by which CUEDC1 promotes tumor growth." (PMID 33099540, 2020). "The immunohistochemical analyses performed on the tumor with total excision revealed negative staining for MDM2 and CDK4." (PMID 31282548, 2020). "IHC detected ER expression levels are not a predictive marker for CDK4/6 inhibitor response, as suggested by the different response to estrogen in ER+ PDX tumor models." (PMID 29963233, 2018). "Fascaplysin has been reported to exert anti-cancer effects by inhibiting cyclin-dependent kinase 4 (CDK4); however, the precise mode of action by which fascaplysin suppresses tumor growth is not clear." (PMID 28961193, 2017). "In IHC, the tumor cells were negative for desmin, S-100, c-Kit, CK-AE1/AE3, EMA, CD31, CD117, CDK4, MDM2 and p63." (PMID 26337721, 2015). "The tumor cells show diffuse strong expression of Factor VIII, Fli-1, INI-1, vimentin, MDM2, and CDK4, local expression of CD31, AE1/AE3, EMA and P63, and no expression of CD34, S-100, actin-sm, desmin, MyoD1, and HMB45." (PMID 26315812, 2015).
tumor (continued). "In contrast to CDK6, high expression of CDK4 in p185BCR-ABL+ leukemic cells did not increase p16INK4a expression, nor was any change in tumor growth observed." (PMID 23948297, 2013). "Immunohistochemical analysis of the resected specimen revealed focal positivity for CD34 and partial positivity for MDM2 in the tumor cells at the resection margin, whereas staining for CD31, AE1/AE3, SMA, desmin, and CDK4 was negative, indicating no specific line of differentiation." (PMID 41334114, 2025). "Whether in tumor or non-tumor cells, TFF3 consistently exhibited upregulation in BL samples from patients who responded well to CDK4/6is." (PMID 39955556, 2025). "Longitudinal ctDNA analysis using a high-sensitivity tumor-informed assay in this study revealed valuable insights into ctDNA dynamics and timing in patients with HR+/HER2−negative MBC undergoing standard endocrine and CDK4/6i therapy." (PMID 40683861, 2025). "Immunohistochemically, the tumor cells are positive for MDM2 and CDK4 and negative for ALK." (PMID 40282503, 2025). "Administration of a very low dosage of C3I-22 could already effectively clear the tumor burden of the transplanted DLD-1 cells and mitigate the levels of pRb and CDK4, and within the period of treatment the mice displayed no severe liver and kidney toxicity." (PMID 38963708, 2024). "Unlike most prior studies on CDK4/6 inhibitor resistance, which focused exclusively on tumor DNA, our study explored both the DNA landscape (via WES) and the transcriptomic landscape (via RNA-seq), using both tumor biopsies and ctDNA." (PMID 38503755, 2024). "After recurrence, one course of pembrolizumab plus anlotinib hydrochloride showed no tumor shrinkage, and genetic testing showed CDK4 amplification and PD-L1 TPS <1%; therefore, the plan was changed to one course of pembrolizumab plus palbociclib, but the tumor still did not shrink." (PMID 38827794, 2024). "Notably, we found that xenografts only formed from the recurrent tumor harboring the gain of PDGFRA and amplification of CDK4 and MDM2, which were not identified in the initial tumor." (PMID 38012788, 2023). "Interestingly, CDK4 expression was not elevated in lenvatinib-resistant HCC cells and lenvatinib-resistant HCC xenograft tumor compared to the corresponding mock controls." (PMID 37872167, 2023). "Combining the CDK4/6 inhibitor palbociclib and the MEK inhibitor trametinib not only reduced growth of patient-derived xenograft models but also enhanced response to PD-1 inhibition in a transplantable tumor model derived from the KPC model." (PMID 35273962, 2022). "Notably, clinical history for patient HT77 indicated that the CDK4/6 inhibitor palbociclib was given to the patient, albeit at a much later phase in the disease’s journey of progression, such that the therapy may not have been able to compete against the increased tumor burden." (PMID 36612255, 2022). "Tumor cells were nonreactive for SF-1, inhibin alpha, desmin, HHF35, HMB45, Melan A, MITF, c-kit, DOG1, cytokeratin AE1/AE3, h-caldesmon, STAT6, CD68, MDM2, CDK4, c17, DHEAST, 3BHSD, CD31, Factor 8, and ERG." (PMID 34797454, 2021). "In contrast, the tumor cells were nonreactive for SF-1, inhibin alpha, desmin, HHF35, HMB45, Melan A, MITF, c-kit, DOG1, cytokeratin AE1/AE3, h-caldesmon, STAT6, CD68, MDM2, CDK4, c17, DHEAST, 3BHSD, CD31, Factor 8, and ERG." (PMID 34797454, 2021). "Moreover, in tumor tissue by uninterrupted slicing and IHC assay we found that an obvious positive correlationbetween ASPM and CDK4 but not CCND1 (data not shown) was existed." (PMID 32742488, 2020). "Interestingly, and contrary to multiple other tumor models, PDA models exhibited disparate responses to CDK4/6 inhibition that were not dependent on the canonical RB-pathways." (PMID 25156567, 2014).